CD247 (CD247 molecule)
Description:
Part of the TCR-CD3 complex present on T-lymphocyte cell surface that plays an essential role in adaptive immune response. When antigen presenting cells (APCs) activate T-cell receptor (TCR), TCR-mediated signals are transmitted across the cell membrane by the CD3 chains CD3D, CD3E, CD3G and CD247/CD3Z. All CD3 chains contain immunoreceptor tyrosine-based activation motifs (ITAMs) in their cytoplasmic domain. Upon TCR engagement, these motifs become phosphorylated by Src family protein tyrosine kinases LCK and FYN, resulting in the activation of downstream signaling pathways. CD247/CD3Z ITAMs phosphorylation creates multiple docking sites for the protein kinase ZAP70 leading to ZAP70 phosphorylation and its conversion into a catalytically active enzyme. Plays an important role in intrathymic T-cell differentiation. Additionally, participates in the activity-dependent synapse formation of retinal ganglion cells (RGCs) in both the retina and dorsal lateral geniculate nucleus (dLGN) (By similarity).
Synonyms: CD3Z; T3Z; TCRZ; CD3H; CD3Q; CD3-ZETA; CD3ZETA; IMD25
Tractability: Small molecule: a structure with a bound ligand is known. Antibody: its Gene Ontology location is reachable by antibodies, with high confidence; UniProt places it where antibodies can reach, with medium confidence; UniProt predicts a signal peptide or a membrane-spanning region. PROTAC: ubiquitination databases record sites on it; its protein half-life has been measured.
Gene: Protein-coding gene on chromosome 1 (167,425,027 to 167,518,640, reverse strand). Ensembl gene ENSG00000198821.
Subcellular location: Cell membrane
Pathways (Reactome):
Immune System: Co-inhibition by PD-1; Downstream TCR signaling; FCGR activation; Generation of second messenger molecules; Immunoregulatory interactions between a Lymphoid and a non-Lymphoid cell; Phosphorylation of CD3 and TCR zeta chains; Regulation of actin dynamics for phagocytic cup formation; Role of phospholipids in phagocytosis; Translocation of ZAP-70 to Immunological synapse
Disease: FCGR3A-mediated IL10 synthesis; FCGR3A-mediated phagocytosis; Nef and signal transduction
Gene Ontology:
Molecular function: identical protein binding; MHC class II receptor activity; protein binding; protein heterodimerization activity; protein homodimerization activity; protein tyrosine kinase binding; protein-macromolecule adaptor activity; transmembrane signaling receptor activity
Biological process: Fc-gamma receptor signaling pathway; protein complex oligomerization; protein-containing complex assembly; T cell receptor signaling pathway; adaptive immune response; alpha-beta T cell activation; cell surface receptor signaling pathway; gamma-delta T cell activation
Cellular component: alpha-beta T cell receptor complex; cytoplasm; Fc-gamma receptor III complex; plasma membrane; T cell receptor complex; gamma-delta T cell receptor complex; membrane; plasma membrane protein complex
Genetic constraint (gnomAD): Loss-of-function variants: 9 observed, 24.81 expected, observed/expected ratio (o/e) 0.36, 90% interval 0.22 to 0.63. The upper end of that interval is the gene's LOEUF score, 0.63, which puts it in group 2 of 6, group 1 being the genes least tolerant of losing a copy. Missense variants: 179 observed, 193.3 expected, observed/expected ratio (o/e) 0.93, 90% interval 0.82 to 1.05. Synonymous variants: 61 observed, 72.16 expected, observed/expected ratio (o/e) 0.85, 90% interval 0.69 to 1.05.
Gene-disease validity (ClinGen):
ClinGen rates the evidence that CD247 causes each of these diseases.
immunodeficiency 25 (autosomal recessive): Definitive. Any severe combined immunodeficiency in which the cause of the disease is a mutation in the CD247 gene.
Homologues: Orthologues: chimpanzee CD247 (99% identical), guinea pig CD247 (84% identical), dog CD247 (82% identical), mouse Cd247 (81% identical), pig CD247 (80% identical), rat Cd247 (77% identical), macaque CD247 (65% identical), rabbit CD247 (61% identical), tropical clawed frog cd247 (42% identical).
Diseases named in the same sentence as CD247 in open-access papers:
CD247 is named in the same sentence as 107 diseases in open-access papers, as found by Europe PMC text mining. Sharing a sentence is not in itself a finding about the gene and the disease. The quoted sentences say what the papers report.
Sepsis (13 papers, 2020 to 2025). Sepsis is defined as life-threatening organ dysfunction caused by a dysregulated host response to infection. "This further demonstrates that the poor expression or deficiency of CD247 might lead to incidence and development of sepsis." (PMID 36855106, 2023). "Currently, there are many biomarkers used in the prediction of sepsis prognosis, such as CD247, FYN, CD96, etc., most of which have been studied individually as single biomarkers." (PMID 38755528, 2024). "CD247 is a key gene impacting the prognosis of mouse sepsis and has also been identified as a critical gene for septic shock." (PMID 38404591, 2024). "We found that CD247 was lowly expressed in sepsis through sequencing analysis of human peripheral blood, followed by a lower survival rate." (PMID 36918563, 2023). "Our in vitro cellular experiment revealed lower expression of CD247 in sepsis versus the heathy control, which was statistically significant (p = 0.012), consistent with the RNA-seq result." (PMID 36855106, 2023). "In sepsis, monocytes were negatively correlated with CD247, CD2, and CD40LG, while positively correlated with LCN2 and RETN." (PMID 37822934, 2023). "The expression results of core genes in different samples showed that five genes (BCL9L, BCL11B, CD96, SAMD3 and CD247) were decreased in sepsis samples, compared with the normal group." (PMID 36918563, 2023). "Expression of CD247, IL-2Rβ and TGF-βR3 was positively associated with the survival in patients with sepsis, and expression of IL-1R2 was negatively associated (p < 0.05)." (PMID 36855106, 2023). "The expression of CD247 is gradually downregulated during the development from sepsis to septic shock." (PMID 35190763, 2022). "In previous studies, CD247 in sepsis is also enriched in the T cell pathway and is related to the development and prognosis of sepsis." (PMID 35184642, 2022). "CD247 has been reported to be involved in human and murine sepsis by many studies, and it can be involved in the occurrence and development of sepsis as a key gene of sepsis." (PMID 36527479, 2023). "Sepsis development/progression in mice could be regulated by changing the LPS amount, as an example of using different doses of LPS to set survival and death groups in the discovery of six genes (CD247, DOCK2, IFI35, ITK, LCK and MED25)." (PMID 37456011, 2023). "Hence, our findings offer new insights into the molecular mechanisms underlying COVID-19 and sepsis-induced ARDS and suggest CD3, CD247, CD2, CD40LG MMP-9, LCN2, and RETN as the potential targets for neutrophils in developing novel therapies and diagnostic tools for these diseases." (PMID 37822934, 2023). "We discovered that both CD247 and ARL4C exhibited high levels of expression in the bloodstream of the sepsis-afflicted rat, potentially serving as beneficial immune-inflammatory regulators." (PMID 38404591, 2024). "Drawing upon the insights gleaned from our murine sepsis-induced ARDS model and human subjects afflicted with sepsis-induced ARDS, we selected CD247, CD2, CD40LG, KLRB1, LCN2, and RETN as the foci of our subsequent investigation." (PMID 37822934, 2023). "When comparing the sepsis patients with SIRS cases, CD247, IL-2Rβ and TGF-βR3 were down-regulated significantly but IL-1R2 marginally varied." (PMID 36855106, 2023). "This study identified four core genes, including CD247, IL-1R2, IL-2Rβ and TGF-βR3, with potential to be novel biomarkers for the prognosis of sepsis." (PMID 36855106, 2023). "In vitro experiment was performed to test expression of CD247, IL-2Rβ, TGF-βR3 and IL-1R2 in human THP-1 cells of sepsis." (PMID 36855106, 2023). "Of these, six hub genes (CD247, CD2, CD40LG, KLRB1, LCN2, RETN) showed significant alterations across COVID-19, sepsis, and geriatric sepsis-induced ARDS." (PMID 37822934, 2023).
Sepsis (continued). "Overall, through mouse study and online patient data analysis, five genes (CD247, DOCK2, IFI35, ITK, and LCK) were reported to positively correlate with sepsis prognosis whilst only the expression of MED25 displayed a negative correlation." (PMID 37456011, 2023). "In vitro cellular experiment showed up-regulated expression of IL-1R2 while down-regulated of CD247, IL-2Rβ, TGF-βR3 in sepsis patients." (PMID 36855106, 2023). "Our findings revealed significant decreases in CD4, CD3e, IL-7R, CD5, CD247, CD2, CD40LG, ITK, and KLRB1, and significant elevations in MMP9, LCN2, and RETN in sepsis-induced ARDS compared to controls." (PMID 37822934, 2023). "BCL9L, BCL11B, CD247, CD96 and SAMD3 were decreased in sepsis and mainly expressed in the T cell; while MAFG increased in sepsis and localizes to monocytes." (PMID 36918563, 2023). "In conclusion, the present study revealed an unbalanced immune response at the transcriptome level of sepsis and identified genes for potential biomarkers of sepsis, such as ITK, CD247, MMP9, CD3D, MMP8, KLRK1, and GZMK." (PMID 35190763, 2022). "S1PR5, GNLY, CD247, KLRG1, IL-1R2, AUTS2, IL-2Rβ, ARG1, TGFBR3, TLR5 and PRF1 in the top 80 genes in the two modules were located toward the center of the co-expression network, and CD247, IL-2Rβ, TGF-βR3 and IL-1R2 were identified as core genes in sepsis." (PMID 36855106, 2023). "CD247, DOCK2, IFI35, ITK, LCK, and MED25 might be important targets affecting the prognosis of sepsis." (PMID 33015708, 2020). "Moreover, we found that CD3, CD247, CD2, and CD40LG were negatively correlated with KC, whereas MMP-9, LCN2, and RETN were positively correlated with KC, suggesting that these candidate hub genes may regulate geriatric sepsis-induced ARDS by modulating the recruitment of neutrophils to the lung." (PMID 37822934, 2023). "CD247, CD2, CD40LG, and KLRB1 displayed a positive correlation with CD8+ T cells and CD4+ T cells in both COVID-19 and sepsis cases, while LCN2 and RETN showed a negative correlation." (PMID 37822934, 2023). "Results revealed a negative correlation between neutrophils and CD247, CD2, and KLRB1, and a positive correlation with RETN in both COVID-19 and sepsis." (PMID 37822934, 2023).
autoimmune disease (11 papers, 2011 to 2025). A disorder resulting from loss of function or tissue destruction of an organ or multiple organs, arising from humoral or cellular immune responses of the individual to their own tissue constituents. "The non-coding sequence polymorphism of CD247 is under strict regulation and correlated with multiple immune responses and autoimmune diseases." (PMID 36855106, 2023). "Dysfunction of T cells by downregulation of gene CD247 has been shown in a variety of chronic conditions, including cancer, autoimmune diseases, and infectious diseases." (PMID 38571958, 2024). "CD247 downregulation also occurs in autoimmune diseases and inflammation with various etiologies and physiology." (PMID 37461343, 2023). "Studies have shown that the gene CD247 is also involved in other autoimmune diseases, such as systemic lupus erythematosus, rheumatoid arthritis, and systemic sclerosis, which shows that CD247 is closely related to the occurrence of autoimmune diseases." (PMID 35190763, 2022). "Studies have shown that abnormalities in CD247 are associated with chronic inflammation-induced immune disorders, including chronic infections (HIV, hepatitis C, and leprosy) and autoimmune diseases (arthritis, contact eczema, and lupus)." (PMID 35184642, 2022). "Down regulation of CD247 and LCK has been associated with other autoimmune diseases, tumours and chronic infections all of which are associated with persistent exposure to antigen." (PMID 23977094, 2013). "Taking into account the role of CD247 in the response of the T-cells, its entailment in autoimmune diseases and in order to better clarify the role of this gene in RA susceptibility, we aimed to analyze CD247 gene variants in a large independent European Caucasian cohort." (PMID 23861880, 2013). "We found that CD247, IL2RB and IL2 ranked 32th, 34th and 39th, respectively, and have been associated with RA in follow-up study of GWAS and studies exploring shared susceptibility loci among autoimmune diseases." (PMID 21980439, 2011). "Additionally, key genes such as IL2RA and CD247, linked with risk genes PTPN22, PTPN2, and RUNX1, are consistently implicated across multiple conditions, including RA, lupus erythematosus, B-cell lymphomas, and autoimmune diseases." (PMID 40839671, 2025). "Furthermore, CD247 is known to be down-regulated in other autoimmune diseases." (PMID 23977094, 2013).
Immunodeficiency (9 papers, 2018 to 2025). Failure of the immune system to protect the body adequately from infection, due to the absence or insufficiency of some component process or substance. "Here, we compared the capacity of CD247 somatic variants in two immunodeficiency cases with severe CD247 germline changes (p.M1T and p.Q70X) to restore TCR expression and function in different T cell models, both human and murine." (PMID 40711587, 2025). "Reported CD247-deficient patients showed severe immunodeficiency despite the presence of two populations of peripheral T cells, most with low TCR levels carrying the germline variant and a few with higher TCR levels due to somatic reversion." (PMID 40711587, 2025). "Similarly, DOCK2 interacts with CD247, which is implicated in an immunodeficiency with similar clinical manifestations." (PMID 33893283, 2021). "The analysis revealed the significant enrichment of genes such as HLA-DQB1, HLA-DPA1, S100A8, SFRP1, CD247, CTSH, and LAMP3, which are linked to inflammatory and immune disease pathways." (PMID 40426861, 2025). "Last but not least, CD247 was thought to be involved in the recognition and presentation of tumor cells in the immune system, and its loss of function can lead to the development of immunodeficiency." (PMID 34795691, 2021).
Hypertension (7 papers, 2015 to 2025). The presence of chronic increased pressure in the systemic arterial system. "A genome-wide association study identified CD247 as a candidate gene for hypertension in humans." (PMID 40810662, 2025). "The CD247 KO rat has been used to illustrate a direct role for T cells in salt-induced hypertension in male Dahl rats." (PMID 40810662, 2025). "For example, the target genes CCR7 and CD247 were shown to be involved in the regulation of immune inflammatory cell function, contributing to end organ damage in hypertension." (PMID 32338289, 2020). "More recently, Rudemiller offered data in support of a role for CD247 in hypertension that is mediated by altered immune cell function." (PMID 26207811, 2015). "However, since CD247 KO attenuated the development of hypertension, this concern is somewhat mitigated." (PMID 40810662, 2025). "In addition, knockout of CD247 reduced the hypertension levels by decreasing immune cell infiltration into the kidneys, potentially serving as a therapeutic target to delay the progression of AAA." (PMID 38785203, 2024). "CD247 plays a central role in hypertension, but this gene might be involved in the HF." (PMID 34218797, 2021). "The Mattson lab demonstrated that the development of hypertension in Dahl S rats on a high salt diet was attenuated in Rag1 -/- Dahl S rats (lacking T and B cells) and CD247 -/- Dahl S rats (lacking functional T cells)." (PMID 39361560, 2024). "Our data demonstrate that the attenuation of BP in CD247 KO rats on a HFD was unlikely due to differences in fat consumption, body weight, or overall changes in body fat content, supporting an inflammatory basis, rather than a metabolic one, for the development of HFD-induced hypertension." (PMID 40810662, 2025).
systemic lupus erythematosus (7 papers, 2011 to 2024). An autoimmune multi-organ disease typically associated with vasculopathy and autoantibody production. "They provided evidence of association with known MHC loci, but only one ‘new’ locus was identified at CD247 in the US/European dataset, variants at CD247 being known to contribute to the susceptibility of systemic lupus erythematosus." (PMID 21750679, 2011). "Previous studies found that CD247 were associated with Systemic lupus erythematosus (SLE) and other autoimmune disorders by T cell-mediated mechanism." (PMID 33344378, 2020). "It is known that CD247 is related to the pathogenesis of systemic lupus erythematosus and hypertension." (PMID 36918563, 2023). "Research reported that in cases of systemic lupus erythematosus (SLE), more than a half had attenuation or deficiency of CD247 expression." (PMID 36855106, 2023). "The abnormal regulation of CD247 has been reported in chronic inflammatory diseases such as celiac disease, chronic obstructive pulmonary disease, systemic lupus erythematosus, and systemic sclerosis." (PMID 35184642, 2022).
systemic sclerosis (7 papers, 2012 to 2024). A chronic disorder, possibly autoimmune, marked by excessive production of collagen which results in hardening and thickening of body tissues. "SNPs within the CD247 gene, encoding the CD247 protein, have been implicated in many connective tissue disorders, including systemic sclerosis (SSc)." (PMID 38790215, 2024). "CD247 (also known as CD3 chain) is involved in the activation and function of T cells and is one of the susceptibility genes of systemic sclerosis with pulmonary fibrosis." (PMID 34646338, 2021). "No previous study has shown association between T1D/AITD and CD247, but variants in the gene have been associated with systemic lupus erythematosus (SLE), rheumatoid arthritis (RA) and systemic sclerosis." (PMID 27716086, 2016). "The CD247 molecule (CD247, as known as T-cell surface glycoprotein CD3 zeta chain) has been reported as a susceptibility locus in systemic sclerosis, but its correlation with IPF remains unclear." (PMID 34880861, 2021). "Furthermore, downregulation of CD247 had been reported in chronic inflammatory diseases such as celiac disease, chronic obstructive pulmonary disease, systemic lupus erythematosus, and systemic sclerosis." (PMID 34880861, 2021).
idiopathic pulmonary fibrosis (6 papers, 2021 to 2025). Idiopathic pulmonary fibrosis (IPF) is a nonneoplastic pulmonary disease that is characterized by the formation of scar tissue within the lungs in the absence of any known cause. "Recent evidence has demonstrated that CD247 is a potential T-cell–derived disease severity and prognostic biomarker in patients with idiopathic pulmonary fibrosis." (PMID 35774508, 2022). "The low expression of CD247 and the decrease in the number of mature T-cells are common features among thymomas, specific pulmonary fibrosis, rheumatoid arthritis, and systemic lupus erythematosus." (PMID 35774508, 2022). "In addition, studies have pointed out that CD247 can be used as a potential biomarker for evaluating the severity of T cell-derived disease in patients with idiopathic pulmonary fibrosis." (PMID 35184642, 2022). "Two genes, CD247 and CD226, are known to be involved in T-cell activation and function, but their specific role in the development of pulmonary fibrosis remains unclear." (PMID 40843700, 2025). "Considering the condition that the p-value of survival analysis was less than 0.01 and the p-value of expression difference was less than 0.01, we found that ITK, ZAP70, CD247, and LCK were lower expressed in patients with specific pulmonary fibrosis than in healthy controls." (PMID 35774508, 2022).